IL10 (interleukin 10)
Diseases named in the same sentence as IL10 in open-access papers (continued):
Sharing a sentence is not in itself a finding about the gene and the disease.
cancer (continued). "HBsAg induces a large number of cytokines, including transforming growth factor β and interleukin-10, which might increase susceptibility to develop cancer." (PMID 36320009, 2022). "High mobility group box 1 protein (HMGB1) present in exosomes derived from hepatocarcinoma cells induces a population of IL-10-secreting TIM-1+Bregs (CD5highCD24-CD27−/+CD38+/high) which is associated with advanced stages of cancer development and reduced patient survival." (PMID 35350071, 2022). "IL-10 is a pleiotropic cytokine with anti-inflammatory property and immunoregulatory function, which is associated with proliferation and apoptosis of various cancers." (PMID 36212428, 2022). "Follicular helper T cell-mediated suppression of IL-10+ B cells may increase the risk of GC development; once cancer develops, suppression of IL-10+ B cells may enhance overall antitumor immunity." (PMID 35509706, 2022). "Moreover, IL-10 is involved in the abnormal proliferation of breast ducts and lobules and stimulates mitotic activity, leading to increased cancer risk." (PMID 35186043, 2022). "PD-1 blockade is associated with an increase in pro-inflammatory cytokine activity, such as increased circulating levels of interferon-gamma (IFNγ) and interleukin-10 (IL-10), which have positive implications for cancer treatment but can increase the risk of secondary irAEs." (PMID 34201529, 2021). "High IL-10 levels were associated with a worse prognosis in patients with KRAS mutated cancers." (PMID 33777798, 2021). "IL-10 functions as an essential immunoregulator in inflammation and inflammation-associated cancer." (PMID 34394377, 2021). "IL-10 is a cytokine that inhibits inflammatory responses by helping to inactivate T cell, monocyte, and macrophage function, and its elevation has been associated with various types of cancer, including HL, and outcomes in HL." (PMID 33276546, 2020). "Like IL-6, it has been shown that the expression of IL-4 and IL-10 is associated with cancer 87-89." (PMID 31602271, 2019). "It has been reported that polymorphisms in the IL-1 and IL-10 genes could contribute to determining the background for inflammation in which H. pylori infection might facilitate cancer development." (PMID 31065302, 2019). "STAT3 is not only overexpressed and activated in cancer cells but also in tumor-associated immune cells, inducing the expression of immune-suppression related genes, including IL-6, IL-10, TGF-β and VEGF and driving the escape of cancer cells from immune-mediated elimination." (PMID 31088482, 2019). "In addition, while baseline IL-6 was associated with higher cancer mortality overall and among African-Americans and Whites in this study, the association between IL-10 and cancer mortality remained significant only among Whites in our study." (PMID 31448052, 2019). "It was reported that the binding of PD-L1 to PD-1 may cause T cell apoptosis, anergy, exhaustion, and interleukin-10 (IL-10) expression, suggesting that PD-L1 can act as a defender for PD-L1+ cancer cells from CD8+ T cell–mediated lysis." (PMID 31681606, 2019). "Furthermore, studies have also noted differences in disease prognosis based on the expression levels of various cytokines in numerous cancers, where higher levels of interleukin-6 and interleukin-10 were associated with poorer outcomes." (PMID 29298730, 2018). "Interestingly, deletion of the E. coli gene coding for the toxin colibactin abrogates this increased cancer risk in IL10−/− IBD mouse models, whereas wild type mice colonized with colibactin-producing E. coli do not have an increased cancer risk." (PMID 30386335, 2018). "Thus, IL-10 has an important role in carcinogenesis and it is postulated that it affects cancer risk, specifically for NHL." (PMID 28713071, 2018).
cancer (continued). "Substantial heterogeneities were found among all studies regarding IL-10 -1082A/G polymorphism and overall cancer risk (homozygous: P = 0.025; heterozygous: P < 0.001; dominant: P < 0.001 and allele comparison: P < 0.001), but not under the recessive model (P = 0.242)." (PMID 28977953, 2017). "In view of these properties, we hypothesized that IL-10 gene polymorphisms could influence cancer susceptibility." (PMID 28977953, 2017). "Hence, we performed the present meta-analysis to investigate the association between three polymorphisms in IL-10 gene and cancer susceptibility in the Chinese population." (PMID 28977953, 2017). "IL-10 gene promoter region is highly polymorphic, and three promoter single nucleotide polymorphisms (SNPs) such as -1082A/G (rs1800896), -819T/C (rs1800871) and -592A/C (rs1800872) have been reported to regulate IL-10 expression and alter the susceptibility to various types of cancers." (PMID 28977953, 2017). "Interestingly, FPRP test results revealed that only IL-10 -1082A/G polymorphism was truly associated with an increased overall cancer risk." (PMID 28977953, 2017). "Interestingly, FPRP test results revealed that only the association between IL-10 -1082A/G polymorphism and overall cancer risk remained significant at the prior probability level of 0.1." (PMID 28977953, 2017). "A significant association was found between IL-10 -819T/C polymorphism and overall cancer risk (homozygous: OR = 1.19, 95% CI = 1.00-1.41, P < 0.001; recessive: OR = 1.17, 95% CI = 1.00-1.36, P < 0.001 and allele comparison: OR = 1.08, 95% CI = 1.00-1.18, P < 0.001)." (PMID 28977953, 2017). "In view of above evidence, it would be tempting to speculate that IL-10 genetic alterations may contribute not only to circulating IL-10 variation but also to cancer susceptibility." (PMID 27489033, 2016). "IL-10 is considered as another arm of inflammation associated cancer since both mice and humans deficient in IL-10 developed malignancy, IL-10 was required for the physiological protective, anti-inflammatory effects of CD4+ CD25+ regulatory lymphocytes to interrupt colon carcinogenesis in mice." (PMID 27886105, 2016). "For IL-10 polymorphisms (−592C>A, −819C>T, −1082A>G) and urologic cancer risk, subgroup analyses were performed by stratifying available data according to types of cancer and ethnicity of study population." (PMID 27995011, 2016). "High level of serum IL–10 was significantly associated with worse OS at 1-year (OR = 3.70, 95% CI = 2.81 to 4.87, P < 0.00001), 3-year (OR = 3.33, 95% CI = 2.53 to 4.39, P < 0.0001) and 5-year (OR = 2.80, 95% CI = 1.90 to 4.10, P < 0.0001) of cancer." (PMID 26440936, 2015). "In conclusion, our analyses show that high level of serum IL–10 is associated with worse clinical outcome of cancer patients, which indicates that IL–10 might be a potential biomarker for prognostic prediction and targeted treatment in human cancer." (PMID 26440936, 2015). "Comparing the interaction models of the wild type and mutant proteins, we observed that specific mutations disrupt the interactions, such as between IL-10 and its receptor, IL-10 and A2M, and A2M and its partners, which may disrupt immune regulation in cancer." (PMID 25056661, 2014). "Numerous studies have reported associations between IL-10 polymorphisms and cancer susceptibility." (PMID 24765208, 2014). "Given the important roles of IL-10 in carcinogenesis, it is biological plausible that IL-10 polymorphism might modulate the risk of cancer." (PMID 23460834, 2013). "The overall results suggested that the variant homozygote genotype AA of the IL-10-592C>A polymorphism was associated with a moderately decreased risk of all cancer types (OR = 0.90, 95% CI = 0.83–0.98 for homozygote comparison, OR = 0.92, 95% CI = 0.86–0.98 for recessive model)." (PMID 23460834, 2013). "Stratified analyses of the IL-10 -592C>A polymorphism on cancer risk." (PMID 23460834, 2013).
cancer (continued). "Individuals with a weakened IL-10 mediated inhibitory loop are highly susceptible to the carcinogenic consequences of elevated inflammation and show more frequent inflammation-associated cancers." (PMID 22526791, 2012). "Several studies have shown a link between polymorphisms in IL–1β, IL–6, IL–10 and cancer risk." (PMID 22567049, 2011). "Individuals with a weakened IL-10 and Treg-mediated inhibitory loop are highly susceptible to the carcinogenic consequences of gut bacteria-induced inflammation and show more frequent inflammation-associated cancers." (PMID 21818290, 2011). "IL-10 is widely known as an potent immunosuppressive cytokine associated with cancer." (PMID 21595995, 2011). "Although PCT showed stronger association with septic shock (RR = 2.24, p = 0.001), IL-6 (RR = 8.21) and IL-10 (RR = 4.28) demonstrated superior predictive capacity for this critical outcome, emphasizing the clinical utility of cytokine-based risk stratification in febrile pediatric cancer patients." (PMID 40647525, 2025). "Notably, the combination of IL-6 < 185 pg/mL and IL-10 < 20 pg/mL identified low-risk patients with a septic shock rate of only 0.7%, suggesting clinical utility for risk stratification in febrile pediatric cancer patients." (PMID 40647525, 2025). "In this review, the authors will address the role of IL-10 in cancer, the currently available IL-10-based immunotherapy, the epigenetic regulation of IL-10 and the single nucleotide polymorphisms (SNPs) present in IL-10 that might influence patient responses to therapy." (PMID 38186186, 2024). "Notably, this included TGF-β (TGFB1, TGFB3), drivers of adenosine-mediated immune suppression (NT5E (CD73), ENTPD1 (CD39)), Wnt pathway ligands (WNT7A, WNT4), IL10 and drivers/markers of cancer-associated fibroblast activation (INHBA, WNT7A, TGFB1, FAP, PDGFRA, PDGFRB)." (PMID 39568014, 2024). "In promoter regions, functional polymorphisms of the IL-10 gene such as -592C/A can lead to changes in the affinity of transcriptional factors, thereby altering levels of mRNA expression (dose-dependent effect) of inflammatory cytokines associated with the occurrence of cancer." (PMID 35919032, 2022). "In addition, studies in other cancers have demonstrated that tumor-associated-macrophages may aid in the immune escape of cancer cells and immunosuppression by IL-10 secretion." (PMID 34440865, 2021). "Glufosinate treatment in vitro, as low as 10 μM, recapitulates the effect of MSO on IL10 macrophages, leading to a metabolic reprogramming, associated with a HIF1α‐dependent M1‐like phenotype, that functionally translates into a decreased immune suppression, angiogenesis, and cancer cell invasion." (PMID 32885605, 2020). "Cancer susceptibility and severity may be associated with functional polymorphisms of cytokine genes involved in regulating inflammation; in particular, polymorphisms of IL-6 and IL-10 genes may influence cancer susceptibility and in some cases its prognosis." (PMID 28075340, 2017). "Considering the expression of miR-98 might be associated with the expression of IL-10 in B cells, we measured the expression of IL-10 in peripheral B cells, which were significantly higher (1.55 folds vs 0.21 folds in the healthy group) in the cancer group." (PMID 27605397, 2016). "However, the molecular mechanisms underlying the different impacts of IL10 on different cancer types remain unclear and must be further investigated." (PMID 26956044, 2016). "The present study demonstrated a loss of anti-inflammatory IL-10, during the transition from inflammation to carcinoma formation, and the coordinated promotion of pro- and anti-inflammatory cytokines in the development of carcinoma and metastasis by M2 macrophages." (PMID 25434400, 2015).
cancer (continued). "In contrast, PGE2 can promote the induction of suppressive IL-10 and directly suppresses the production of multiple pro-inflammatory cytokines, which allow it to limit nonspecific inflammation, thereby promoting the immune suppression associated with chronic inflammation and cancer." (PMID 23760060, 2013). "Interestingly, in the colon-26 murine model of cancer cachexia associated with systemic inflammation there appears to be a complex intratumoural amplification loop between IL-1β and IL-6, which can be downregulated by IL-10." (PMID 17088911, 2006). "Specifically, we observed a significant decrease in the levels of MIP-1α, GM-CSF, IL-13, IL-6, IL-10, IL-5, IL-12p70, and IL-4 after SNS administration, all of which are associated with the severity of MMD symptoms and cancer prognosis." (PMID 41491244, 2026). "Many studies tried to evaluate the correlation between cytokines and the pathogenesis of various cancer types and IL-2, IL-6, IL-10, and TNF-α are often target of these analyses." (PMID 40869161, 2025). "This highlights the importance of IL-10 as a potential therapeutic target in age-related immune pathologies and cancer immunotherapy, particularly for inflammaging." (PMID 40788503, 2025). "There were statistically significant differences in indicators such as age, yearly income, alcohol drinking, family history of cancer, high-risk HPV infection, vaginal CD4, CD8,CD4/CD8, and IL-10 levels between the control group and the CIN group." (PMID 41142594, 2025). "Elevated serum IL-10 levels have been detected in BC patients compared to healthy controls; although IL-10 is a poor prognostic factor in several cancer types, it has been correlated with favorable survival outcomes in early-stage BC." (PMID 40868199, 2025). "Recently, cytokines like IL2, IL‐7, IL‐10, and IL‐12 have been tested in clinical trials for the therapy of certain cancers (reviewed elsewhere)." (PMID 38813869, 2025). "Consistently, RCTs in cancer populations have shown that 12 weeks of high-intensity AE lead to greater improvements in IL-6 and IL-10 compared to moderate-intensity AE." (PMID 40895542, 2025). "The IL-10 pathway is a critical immunoregulatory mechanism that plays a complex role in cancer by modulating immune responses." (PMID 40739089, 2025). "Cancer stem cells were shown to contribute to T cell dysfunction by promoting IL-10 and TGF-β, which inhibit CD8+ cytotoxic T cells and induce the expansion of Tregs." (PMID 40160820, 2025). "High IL-10 alongside high IL-6/TNF is sometimes observed in late-stage cancers, indicating a state of chronic inflammatory activation with concurrent immunosuppression." (PMID 41007766, 2025). "Understanding this duality is crucial for developing immunotherapeutic strategies targeting IL-10 or its signaling pathways for chronic inflammatory diseases and cancer." (PMID 40788503, 2025). "Among TAMs released factors, IL-6, IL-10 and IL-8 foster signaling pathways directly involved in stimulating cancer cell proliferation and tumor growth." (PMID 39981232, 2025). "IL‐6 and IL‐10 are pleiotropic cytokines mediating both pro‐ and anti‐tumorigenic roles during cancer development." (PMID 40356340, 2025). "A longitudinal study of 71 cancer survivors suggested that attenuation in IL-1β, IL-6, TNF-α, and IL-10 was associated with either an increased sleep duration or decreased sleep problems." (PMID 41470834, 2025). "Given its diverse sources, multifaceted functions, and the multiple variables that can modulate its signaling activity, targeting IL-10 for cancer immunotherapy presents a formidable challenge." (PMID 40149345, 2025).
cancer (continued). "Interleukin-10 (IL-10) is emerging as a promising cancer immunotherapy due to its ability to boost exhausted immune cells (CD8+ T cells), helping them fight tumors more effectively while also reducing harmful inflammation." (PMID 40149345, 2025). "Within the complex milieu of the TME in cancer, IL-10 can exhibit a dichotomous role, exhibiting antagonistic and stimulatory properties in distinct contexts." (PMID 41376630, 2025). "As a result, SFV-infected cancer cells significantly altered cytokine and chemokine profiles, reducing immunosuppressive factors (e.g., IL-10) and increasing inflammatory mediators (e.g., CXCL10 and CCL4)." (PMID 40547518, 2025). "For cancer, TNFR1 mediated 43.2% of the positive association with IL-10, while there was slight evidence that IL-6 also mediated 13.2% of the association independently of TNFR1 (p = 0.130)." (PMID 41280118, 2025). "Specifically, Th2 cells promote cancer cell proliferation by secreting cytokines, such as IL-4 and IL-10, driving macrophage differentiation to the M2 phenotype." (PMID 40801655, 2025). "In fact, cancer cell proliferation and metastasis are enhanced by IL-10 through the regulation of antitumor immunity." (PMID 40933989, 2025). "As a result of cancer cell immuno-modulation, several researchers have suggested the increased production of interleukin-10 (IL-10) in NSCLC cells." (PMID 41378291, 2025). "IL-10 is an anti-inflammatory cytokine that functions as a key mediator of anti-cancer strategies by activating CD8+ T cells." (PMID 40150133, 2025). "What’s more, E2, E6 and E7 increase the generation and secretion of interleukin 10 (IL-10) that can aid cancer cells to escape immunologic surveillance." (PMID 39856040, 2025). "The reference lists of all selected articles were further reviewed to identify additional studies relevant to IL-10 in cancer treatment." (PMID 40149345, 2025). "Nevertheless, the clinical application of IL-10 for cancer immunotherapy is restricted by severe hematological toxicity." (PMID 41406970, 2025). "Currently, very few circRNAs are known to regulate IL‐10 signaling in cancer; their function and mechanism of action are listed in." (PMID 40356340, 2025). "VEGFA, IL-10, and prostaglandin E2, produced by cancer cells, collectively induce the upregulation of FasL in TECs." (PMID 40136652, 2025). "As cytokines involved in cancer progression, neutralizing inhibitors targeting IL-1, IL-4, TGFβ, and IL-10 have shown the potential to improve cancer." (PMID 41341593, 2025). "We next measured the secretion of the proinflammatory cytokine TNFα and the anti-inflammatory cytokine IL10 in cocultures of human macrophages and cancer cells (5:1 ratio) incubated with engineered antibodies." (PMID 41128663, 2025). "In this context, this review specifically underscores the progress and challenges in IL-10-directed cancer immunotherapies, highlighting recent advancements in the field." (PMID 40149345, 2025). "IL-10, one of the earliest identified cytokines, has the ability to suppress cancer development and metastasis by modulating inflammation and immune responses." (PMID 40181976, 2025). "Restimulation of splenocytes with L. casei in vitro showed an increase in IFN‐γ secretion, more prominent 7 days post–cancer cell injection, while IL‐10 production was unaffected." (PMID 41221154, 2025). "The concurrent upregulation of IL-10 and IL-17 underscores the interactive balance between pro- and anti-inflammatory responses in the immune system as modulated by cancer." (PMID 40346687, 2025). "Dysregulation of IL-10 signaling can contribute to chronic inflammation and diseases, including cancer." (PMID 40933989, 2025). "Recent studies have highlighted the importance of IL-10 in cancer therapy, as it can promote antitumor immunity while reducing inflammation-associated cancer progression." (PMID 40672135, 2025).